TOB2 (transducer of ERBB2, 2)
Description:
Anti-proliferative protein inhibits cell cycle progression from the G0/G1 to S phases.
Synonyms: TOB4; TROB2; TOBL; bK223H9; APRO5
Tractability: PROTAC: ubiquitination databases record sites on it.
Gene: Protein-coding gene on chromosome 22 (41,433,489 to 41,446,801, reverse strand). Ensembl gene ENSG00000183864.
Subcellular location: Cytoplasm
Subcellular location (Human Protein Atlas): Cytosol
Gene Ontology:
Molecular function: protein binding; transcription corepressor activity; nuclear vitamin D receptor binding
Biological process: female gamete generation; negative regulation of cell population proliferation; regulation of gene expression; negative regulation of DNA-templated transcription
Cellular component: cytoplasm; nucleus
Genetic constraint (gnomAD): Loss-of-function variants: 3 observed, 18.43 expected, observed/expected ratio (o/e) 0.16, 90% interval 0.073 to 0.42. The upper end of that interval is the gene's LOEUF score, 0.42, which puts it in group 1 of 6, group 1 being the genes least tolerant of losing a copy. Missense variants: 407 observed, 468.26 expected, observed/expected ratio (o/e) 0.87, 90% interval 0.8 to 0.94. Synonymous variants: 163 observed, 194.8 expected, observed/expected ratio (o/e) 0.84, 90% interval 0.74 to 0.95.
Homologues: Orthologues: macaque TOB2 (97% identical), pig TOB2 (92% identical), dog TOB2 (92% identical), rat Tob2 (92% identical), rabbit TOB2 (90% identical), mouse Tob2 (90% identical), guinea pig TOB2 (89% identical), tropical clawed frog tob2 (68% identical), Drosophila melanogaster Tob (42% identical), Caenorhabditis elegans fog-3 (16% identical), Caenorhabditis elegans T09B4.6 (8% identical). Paralogues in human: TOB1 (58% identical).
Diseases named in the same sentence as TOB2 in open-access papers:
TOB2 is named in the same sentence as 15 diseases in open-access papers, as found by Europe PMC text mining. Sharing a sentence is not in itself a finding about the gene and the disease. The quoted sentences say what the papers report.
hepatocellular carcinoma (3 papers, 2020 to 2022). A malignant tumor that arises from hepatocytes. "Upregulation of miR-362-3p, which targets and regulates Tob2, thereby promoting the proliferation of hepatocellular carcinoma cells." (PMID 35278064, 2022). "Further, the expression of TOB2 is downregulated in hepatocellular carcinoma tissues, and the anchorage-independent growth of hepatocellular carcinoma cells is also hampered by TOB2 overexpression." (PMID 33435156, 2021). "By contrast, upregulation of miR-362-3p increased cell proliferation and anchorage-independent soft agar growth by directly targeting Tob2 in hepatocellular carcinoma." (PMID 32432112, 2020). "Additionally, a recent study found that the overexpression or knockdown of miR-362-3p increases or decreases the anchorage-independent growth of hepatocellular carcinoma cells, respectively, through targeting TOB2." (PMID 33435156, 2021).
breast carcinoma (2 papers, 2021 to 2025). "Note that Tob2 expression showed a positive correlation with the gene set of “TNFA_SIGNALING_VIA_NFKB” in breast cancer patients." (PMID 40169858, 2025).
brain cancer (1 paper, 2017). A primary or metastatic malignant neoplasm affecting the brain. "Potential correlation between TOB2 and survival outcome was also observed in ovarian and brain cancer." (PMID 28922388, 2017).
colorectal cancer (1 paper, 2017). A primary or metastatic malignant neoplasm that affects the colon or rectum. "TOB2, BTG2 and BTG4 had no expression difference between colorectal cancer and normal tissues." (PMID 28922388, 2017).
idiopathic scoliosis (1 paper, 2012). A scoliosis with no known cause. "Tob2 gene was also differentially expressed at the curve convexity, but its expression was up regulated in the population of group A-Juvenile Idiopathic Scoliosis." (PMID 23259508, 2012). "In paravertebral muscles, out of the 75 VDR responsive genes, Tob2 and Med13 genes differentiate Adolescent and Juvenile type of Idiopathic Scoliosis." (PMID 23259508, 2012). "In paravertebral muscles Tob2 and Med13 genes differentiate Adolescent and Juvenile type of Idiopathic Scoliosis." (PMID 23259508, 2012). "Interestingly Tob2 was also differentially expressed at the curve convexity but appeared to be up regulated in Juvenile Idiopathic Scoliosis." (PMID 23259508, 2012). "Our results indicate that significantly lower concentration of VDRl mRNA found in Adolescent Idiopathic scoliosis group compared with their juvenile peers coincide, at least at the transcriptional level, with the up regulation of Tob2 gene in paravertebral muscles of the curve concavity." (PMID 23259508, 2012).
ovarian carcinoma (1 paper, 2017). A malignant neoplasm originating from the surface ovarian epithelium. "Specifically, low expression of TOB2 was associated with poor overall survival (OS) in ovarian cancer patients." (PMID 28922388, 2017).
scoliosis (1 paper, 2012). A congenital or acquired spinal deformity characterized by lateral curvature of the spine. "Whether differences in expression of VDR dependent genes Tob2 and Med13 in paravertebral muscles of the curve concavity observed between Adolescent and Juvenile Idiopathic Scoliosis group in this study are primary or secondary to the time of the scoliosis evolution merits further investigation." (PMID 23259508, 2012). "Fold change analysis of the results permitted to identify Tob2 and MED13 as VDR responsive genes differentially expressed in Juvenile and Adolescent Scoliosis group in muscular tissue samples of curve concavity." (PMID 23259508, 2012).
Sepsis (1 paper, 2019). Sepsis is defined as life-threatening organ dysfunction caused by a dysregulated host response to infection. "Interestingly, several of the genes linked to glucocorticoid signaling (Arl4d, Cdkn1a, Ddit4, Fkbp5, Gjb6, Il6ra, Klf15, Nfkbia, Rhob, Sdc4, Sgk1, Sult1a1, Tob2, Wipf3) and apoptotic process were still upregulated 4 days post-sepsis." (PMID 31278440, 2019).
cancer (6 papers, 2012 to 2025). A tumor composed of atypical neoplastic, often pleomorphic cells that invade other tissues. "BTG1 belongs to the BTG/TOB family of anti-proliferative genes (BTG1-BTG4, TOB1 and TOB2) implicated in several types of cancer." (PMID 22359517, 2012). "TOB2, a member of the anti-proliferative TOB/BTG family, has been implicated in regulating cell growth, apoptosis, and differentiation in several cancer types and cardiovascular conditions." (PMID 41316500, 2025). "Downregulation of TOB2 was found in cancers based on 14 studies but overexpressed in seven analyses." (PMID 28922388, 2017). "Many BTG proteins such as BTG4, TOB1, TOB2 are aberrantly expressed and serve as negative regulators in tumorigenesis in various cancers." (PMID 24147003, 2013). "BTG1 belongs to the BTG/TOB family of anti-proliferative genes (BTG1-BTG4, TOB1 and TOB2) and expression of their gene products is altered in a variety of different cancers." (PMID 22359517, 2012). "As for TOB2, there are few current studies on its relationship with cancer." (PMID 28922388, 2017). "In our study, we observed TOB2 was at a lower expression level in most cancers." (PMID 28922388, 2017). "In the present study, we comprehensively analyzed the role of TOB1, TOB2, BTG1, BTG2, BTG3 and BTG4 in cancer from the perspective of bioinformatics." (PMID 38062199, 2023). "Through a series of bioinformatics analysis, the findings in our study supported the important role of TOB1, TOB2, BTG1, BTG2, BTG3 and BTG4 in pan-cancer and provided a reliable basis for detecting biomarkers of cancer." (PMID 38062199, 2023). "We used bioinformatics methods to analyze the characteristics of TOB1, TOB2, BTG1, BTG2, BTG3 and BTG4 in pan-cancer." (PMID 38062199, 2023).
tumor (6 papers, 2013 to 2023). "Mechanistic investigations reveal that miR-378 overexpression can downregulate the expression of Transducer of ERBB2 (TOB2), a potential tumor suppressor, while miR-378 silencing can enhance the TOB2 expression." (PMID 25427638, 2015). "Moreover, MiR-378 promotes cellular transformation, at least in part, by targeting and inhibiting TOB2, which is further elucidated as a candidate tumor suppressor to transcriptionally repress proto-oncogene cyclin D1." (PMID 24147003, 2013). "StromalScore and ImmunoScore were used to analyze the correlation between APRO (TOB1, TOB2, BTG1, BTG2, BTG3 and BTG4) expression and tumor purity and tumor microenvironment characteristics." (PMID 38062199, 2023). "In addition to the targets that we identified by RNA sequencing, miR-378a-5p has been shown to be involved in tumorigenesis and tumor maintenance by regulating SUFU, TUSC2, TOB2, GABPA and ESRRg." (PMID 24651706, 2014).
infection (1 paper, 2019). The state of being infected such as from the introduction of a foreign agent such as serum, vaccine, antigenic substance or organism. "In differentiated 3T3-L1 cells after 3-day adipogenic treatment, transfection with miR-20a-5p mimics decreased TOB2 protein while miR-20a-5p inhibitor or Sponge LV increased TOB2 protein as well, demonstrating the efficacy of transfection or infection in the differentiated cells." (PMID 31969862, 2019).
TOB2 also shares sentences with these, for which no sentence is quoted: colon adenocarcinoma (1 paper); nasopharyngeal carcinoma (1); osteoporosis (1); uterine corpus endometrial carcinoma (1).